ANGPTL3 (angiopoietin like 3)
Diseases named in the same sentence as ANGPTL3 in open-access papers (continued):
Sharing a sentence is not in itself a finding about the gene and the disease.
diabetes (continued). "Given that obesity, diabetes, and lipid profiles are inter-connected, we aimed in this study to evaluate the association of this GALNT2 rs4846914 variant with metabolic traits, including the obesity traits and related biomarkers, such as Apolipoproteins and ANGPTL3, in a cohort of Arab individuals." (PMID 35885984, 2022). "Taken together, in the context of diabetes, we speculate that reduced ANGPTL3 in female diabetic patients might jeopardize its inhibitory effect on EL, weaken its association with SAA and adversely affect apoA-I stability, all of which would contribute to reduced apoA-I level and HDL dysfunction." (PMID 27620179, 2016). "ANGPTL3 could be considered as a novel therapeutic target for HDL metabolism for treating diabetes." (PMID 27620179, 2016). "Strengths of this study include the use of two distinct mouse models of diabetes to increase scientific rigor, and, similar to therapeutics considered for human cardiovascular outcome trials, use of liver-targeted APOC3 and ANGPTL3 GalNAc ASOs." (PMID 40709279, 2025). "In this study, we investigated ANGPTL3 bound to HDL and explored the effect of ANGPTL3 in HDL on the function of HDL, determined the relationship between ANGPTL3 in HDL and other components in human and mice with non-diabetes or type 2 diabetes mellitus." (PMID 38462608, 2024). "In this study, we confirmed that ANGPTL3 mainly bound to HDL and was a component of HDL in human and mice with non-diabetes or T2DM." (PMID 38462608, 2024). "Moreover, in the setting of diabetes, APOC3 silencing appears to have beneficial effects beyond those of ANGPTL3 silencing, preventing arterial free cholesterol accumulation." (PMID 40709279, 2025). "Diabetes induced the upregulation of serum TNF-α, IL-6, and IL-1β, and treatment with anti-ANGPTL3/IL22 showed prominent reversal compared with mIL22Fc or anti-ANGPTL3 alone." (PMID 36544775, 2022). "Increased levels of ANGPTL3 are observed in subjects with type 2 diabetes mellitus (T2DM) in comparison with nondiabetic subjects." (PMID 30944669, 2019). "ANGPTL3 was associated with ANGPTL8 in the non-diabetic subjects, whereas, ANGPTL4 was associated with ANGPTL8 in the obese subjects regardless of their diabetes status." (PMID 27733177, 2016). "However, our study suggests that a significant correlation between ANGPTL3 levels and glucose metabolism markers is lacking in patients with diabetes." (PMID 34293055, 2021). "However, which ANGPTL—ANGPTL3, 4, or 8—exerts the largest effect on the plasma TG levels of diabetes patients has not been investigated thus far." (PMID 34293055, 2021). "Patients with PAS had a significantly higher percentage of diabetes (p = 0.002), older age (p = 0.030), higher systolic blood pressure (p = 0.016), higher fasting glucose (p = 0.008), serum C-reactive protein (p = 0.002), and ANGPTL3 level (p = 0.001) than those without PAS." (PMID 34684048, 2021). "The elevated plasma ANGPTL3 in the autoimmune diabetes model, but not in the STZ diabetes model tracked with the more severe hyperlipidemia in that model." (PMID 40709279, 2025). "Here, we examined whether ANGPTL3, as a component of HDL, modulates HDL function and affects HDL other components in human and mice with non-diabetes or type 2 diabetes mellitus." (PMID 38462608, 2024).
Obesity (29 papers, 2014 to 2025). Accumulation of substantial excess body fat. "Among the BMI-SDS-associated proteins is ANGPTL3, which has shown variable associations with BMI and obesity in previous studies." (PMID 39972214, 2025). "Its significant correlation with BMI and WC further confirmed the association between ANGPTL3 and obesity." (PMID 34422408, 2021). "The decreased level of adiponectin and increased levels of leptin, c-peptide, insulin and angiopoietin-like 3 protein were associated with metabolically healthy and unhealthy obesity." (PMID 34947881, 2021). "Our key findings were the robust POE of variants at the LPL and DOCK7/ANGPTL3 loci on obesity measures in both family cohorts, and the same variants also showed POE on lipid traits in the Botnia family study." (PMID 35052431, 2021). "The associations between ANGPTL3, lipoprotein metabolism and liver health status have been analyzed in the DiOGenes (diet, obesity, and genes) study." (PMID 33451033, 2021). "Variants at LPL and DOCK7/ANGPTL3 showed POE on obesity-related traits in Botnia and HTB, and POE effects on obesity were seen to a higher degree in daughters." (PMID 35052431, 2021). "This study was designed to examine the miR-181d expression levels in obesity and to investigate its association with ANGPTL3." (PMID 31413305, 2019). "Thus, ANGPTL3 is linked tightly to lipid metabolism, and its aberrant expression has been linked to obesity and type 2 diabetes." (PMID 34422408, 2021). "One of the main limitations of this study is the cross-sectional design which did not allow us to establish causality regarding the roles that miR-181d and ANGPTL3 may therefore play in the development of obesity." (PMID 31413305, 2019). "In conclusion, we have comprehensively investigated the association between ANGPTL3, 4 and 8 in obesity and T2D in plasma and adipose tissue showing for the first time that ANGPTL 4 and 8 are increased in human subjects with T2D compared to non-diabetic subjects." (PMID 27733177, 2016). "Evaluation of major parameters of cardiovascular dysfunction concerning ANGPTL2 and ANGPTL3, especially in a cohort design, is highly recommended for future research to establish the connection between these markers and risk of cardiovascular diseases that generally accompany obesity." (PMID 34422408, 2021). "In the previous study from our group, we noticed significantly higher levels of ANGPTL8 in apparently healthy women with obesity whereas ANGPTL3 levels were comparable." (PMID 35736472, 2022). "Of note, a cluster analysis of various adipokine serum levels identified Angptl3 as a factor related with parameters of obesity and inflammation." (PMID 34951653, 2022). "Angptl3 is commonly related to obesity, lipolysis (it acts as an inducer of lipolysis) and inflammation." (PMID 34951653, 2022). "In the current study, we aimed to examine the probable relationship of serum ANGPTL2 and ANGPTL3 levels with obesity and its relevant metabolic parameters in children." (PMID 34422408, 2021). "Sex-specific parental effects were also observed; variants at ANGPTL3/DOCK7 showed POE on lipid traits and obesity in daughters only, while those at LPL and TMEM57 showed POE on lipid traits in sons." (PMID 35052431, 2021). "Further prospective studies are necessary to evaluate the link between ANGPTL2 and ANGPTL3 concentrations and cardiovascular outcomes of obesity." (PMID 34422408, 2021). "The ob/ob mice, vaccinated with a peptide targeting ANGPTL3, also exhibited a marked decrease in diet-induced obesity and hepatic steatosis, suggestive of the metabolic impact of ANGPTL3 on NAFLD." (PMID 34944728, 2021). "Multiple members of this protein family are closely related to obesity and obesity-related metabolic diseases: ﻿ANGPTL3, ANGPTL4, and ANGPTL6 can directly regulate lipid, glucose, and energy metabolism without exerting angiogenic effects." (PMID 32299395, 2020).
Obesity (continued). "This study was designed to evaluate the expression of miR-181d in obesity and to shed light on its role in lipid metabolism by modulating an important lipid-regulating protein, ANGPTL3." (PMID 31413305, 2019). "The inverse relationship between miR-181d and ANGPTL3 and the opposing roles of these molecules in lipid metabolism support the concept that miR-181d has a protective role against obesity." (PMID 31413305, 2019). "The findings support both the regulatory and protective roles of miR-181d against obesity by modulating ANGPTL3 expression." (PMID 31413305, 2019). "Taken together, ANGPTL3 and 4 levels are affected by acute as well as chronical nutritional and metabolic status; however, their potential role in the pathogenesis of obesity and T2DM requires further investigation." (PMID 29695708, 2018). "Analogously, the presence of obesity significantly increased ANGPTL4 while tending to reduce ANGPTL3 suggesting body weight as one of the main regulators of ANGPTL levels." (PMID 29695708, 2018). "Taken together, these findings suggest that different mechanisms are involved in the dysregulation of ANGPTL3 and ANGPTL4 in patients with increased adiposity or, alternatively, that diverse metabolic abnormalities stem from the obesity-associated changes in circulating ANGPTL3 and ANGPTL4." (PMID 34440242, 2021). "The increased concentration of ANGPTL3 in obesity may also be due to the reduced level of some microRNAs such as miR-181d that inhibits the expression of ANGPTL3." (PMID 34422408, 2021). "However, previous studies have shown that ANGPTL3 levels are abnormally increased in insulin-resistant state and obesity, with worsening glucose metabolism and enhancing lipolysis in adipose tissues." (PMID 33273510, 2020). "This suggests that ANGPTL5 could be a specific and a more sensitive marker for childhood as well as adult obesity than ANGPTL3 and ANGPTL8." (PMID 32286392, 2020). "Taken together, our data support the protective role that miR-181d may play against obesity by reducing ANGPTL3 gene expression." (PMID 31413305, 2019). "In obesity and T2D subjects, the ANGPTL3 level was higher than that in healthy subjects." (PMID 29951533, 2018). "Taken together, our data suggest that serum ANGPTL3 and 4 levels are influenced by nutritional status and fasting and could be involved in the metabolic disturbances present in obesity and AN." (PMID 29695708, 2018). "In conclusion, our data shows that ANGPTL3, 4 and 8 are increased in obesity and T2D." (PMID 27733177, 2016). "Additionally, ANGPTL3 is typically downregulated by leptin and insulin, and, therefore, resistance to leptin and insulin that generally happens in obesity may be responsible for its elevated levels." (PMID 34422408, 2021). "This study aims to explore the combined role of ANGPTL3, 4, 8, omentin-1, leptin, TNF-α, and IL-6 molecules known for their roles in fat metabolism, obesity, and inflammation, yet whose connection to PCOS is still debated in the development of PCOS." (PMID 41341944, 2025). "The disinhibition of lipolysis commonly seen in obesity-related insulin resistance (a condition characterized by high insulin levels that fail to exert their action due to receptor resistance) could be mediated - at least in part—by reduced Angptl3 concentrations." (PMID 34951653, 2022). "For several adipokines (ANGPTL3, DLL1, chemerin, clusterin, leptin, Nampt, resistin, GPX3), we identified a close relationship with parameters of obesity (BMI, waist circumference, body fat mass), but also inflammation (hsCrP)." (PMID 24968098, 2014). "Our findings showed a strong positive correlation between ANGPTL2 and ANGPTL3, independent of obesity and BMI status." (PMID 34422408, 2021). "The majority of investigations have reported increased circulating ANGPTL3 in patients with obesity or T2D, whereas other studies have found that the plasma levels of ANGPTL3 are not higher in obese individuals than in controls." (PMID 34440242, 2021).
Obesity (continued). "Following miR-181d transfection, the expression of ANGPTL3 was significantly reduced compared with the control (no mIR-181d), supporting the anti-obesity role of miR-181d through binding and inhibition of ANGPTL3 expression." (PMID 31413305, 2019). "As both ANGPTL3 and ANGPTL4 are important in lipid metabolism through their interaction with lipoprotein lipase, our data suggest a role for ANGPTL5 in TGL metabolism in obesity." (PMID 31396158, 2019). "Since ANGPTL3, DLL1 and GPX3 are found in the same cluster, our data may stimulate further research characterizing the potential role of ANGPTL3, DLL1 and GPX3 in obesity, altered glucose metabolism and inflammation." (PMID 24968098, 2014). "Compared to the lean subjects (n = 42), circulating ANGPTL3 was elevated (both p > 0.001) in the patients with metabolically unhealthy obesity (MUO; n = 87) and type 2 diabetes (T2D; n = 31), but not in those with metabolically healthy obesity (MHO; n = 48, p > 0.05)." (PMID 34440242, 2021). "Unlike ANGPTL4, the relationship of ANGPTL3 and obesity and T2DM is less clear." (PMID 29695708, 2018). "Similarly, our data show a significant reduction in serum ANGPTL3 in both diabetic groups (VLCD and bariatric surgery) compared to healthy controls, whereas simple obesity was associated only with a nonsignificant trend to reduction." (PMID 29695708, 2018).
Insulin resistance (22 papers, 2014 to 2025). Increased resistance towards insulin, that is, diminished effectiveness of insulin in reducing blood glucose levels. "Previous studies clearly demonstrated that the pathology associated with excess ANGPTL3 causes impaired glucose tolerance and increases insulin resistance in healthy individuals." (PMID 34293055, 2021). "In this study, we evaluate the impact of ANGPTL3 variants on levels of irisin and markers associated with lipid metabolism and insulin resistance." (PMID 34067751, 2021). "Accordingly, in a cross-sectional study, ANGPTL3 concentration was independently associated with insulin resistance (assessed by the HOMA-IR)." (PMID 30944669, 2019). "ANGPTL3 is expressed and release by the liver and works as a regulator of plasma triglyceride levels, positively associated with glycemia, and insulin levels in patients with insulin resistance." (PMID 33807959, 2021). "At baseline, ANGPTL8 concentrations were positively associated with triglycerides (TG) (r = 0.168, P = 0.010), whereas ANGPTL3 levels were associated with fasting insulin (r = 0.248, P < 0.001) and the homeostasis model assessment of insulin resistance (HOMA-IR) (r = 0.197, P = 0.002)." (PMID 26739706, 2016). "While some (such as FGF-21, irisin, adiponectin, klotho, and osteocalcin) have protective effects, others (such as myostatin, fetuin-A, visfatin, and ANGPTL3) exacerbate insulin resistance, inflammation, and fibrosis." (PMID 41373697, 2025). "The molecular mechanisms whereby ANGPTL3 inhibition influences both hepatic and peripheral insulin resistance and the overall effects on glucose metabolism and hepatic steatosis require further investigation." (PMID 38009403, 2023). "Angiopoietin-like protein 3 (Angptl3) is a secreted glycoprotein that plays a crucial role in the regulation of angiogenesis, stem cell proliferation, insulin resistance, lipid metabolism, and tumors." (PMID 37638046, 2023). "Our findings illustrate the key role that the ANGPTL3 plays in connection between lipid metabolism and insulin resistance." (PMID 34067751, 2021). "The correlation between serum ANGPTL3 levels and biochemical, hormonal variables, anthropometric and insulin resistance indices was investigated as well." (PMID 33927698, 2021). "Recent data indicate a positive correlation of ANGPTL3 with plasma glucose, insulin, and homeostatic model assessment of insulin resistance (HOMA-IR) in insulin-resistant states." (PMID 30944669, 2019). "Therefore, inhibition of ANGPTL3 has a protective effect on insulin resistance, lipid metabolism, and hepatic steatosis." (PMID 39409124, 2024). "However, a differential involvement and cross-talk of Angptl3 with fatty acids in the context of lipolysis, lipoprotein lipase pathway, insulin resistance, and inflammation is highly probable." (PMID 34951653, 2022). "This could be partially explained by the elevation of FFAs and the subsequent hepatic and peripheral insulin resistance due to ANGPTL3-induced lipolysis." (PMID 30944669, 2019). "A positive correlation was found between ANGPTL3 and plasma glucose, insulin, and HOMA-IR levels in patients with insulin resistance, and its levels were higher in patients with NASH/MASH than in patients with simple steatosis." (PMID 39409124, 2024). "ANGPTL3 and ANGPTL4 are proteins whose malfunction is related to dyslipidaemia or insulin resistance." (PMID 34947881, 2021). "A possible mechanism of ANGPTL3-induced deterioration of glucose metabolism is the increment of FFA owing to the enhancement of lipolysis in adipose tissue, which can induce peripheral as well as hepatic insulin resistance." (PMID 30944669, 2019). "Since hepatic insulin resistance and T2DM have been considered sequelae of NAFLD, ANGPTL3 could possibly affect glucose levels by inducing NAFLD through lipolysis and increased FFA flux to the liver." (PMID 30944669, 2019).
Insulin resistance (continued). "Interestingly, recent data show a positive correlation of ANGPTL3 with plasma glucose, insulin, and homeostatic model assessment of insulin resistance (HOMA-IR) in insulin-resistant states, implying that ANGPTL3 may also participate in glucose homeostasis." (PMID 30944669, 2019).
type 2 diabetes (22 papers, 2016 to 2025). "Therefore, the decreased levels of ANGPTL3 put the person at an increased risk for type 2 diabetes development and cardiovascular diseases." (PMID 38140923, 2023). "Altogether, our findings suggest that the decreased levels of ANGPTL3 and 4 may be a causative factor for type 2 diabetes." (PMID 38140923, 2023). "Type 2 Diabetes Mellitus (T2DM) and state of insulin resistance, seem to be tightly associated with dysregulation of angiopoietin-like 3-4-8 system." (PMID 33451033, 2021). "LPL mass and ApoC-III were the same but ANGPTL3 was lower in the group with type 2 diabetes compared with control participants." (PMID 37775612, 2023). "A study of 93 patients with type 2 diabetes and 99 healthy adult controls found that ANGPTL3/8 levels were similar between type 2 diabetes patients and controls, whereas ANGPTL4/8 levels were about twofold higher in patients." (PMID 38160757, 2023). "Taken together, oral lipid tolerance tests should be investigated in obese and type 2 diabetic patients to compare the dynamics of Angptl3 and Angptl4 after lipid uptake." (PMID 34951653, 2022). "This could indicate the possible role of ANGPTL3 in regulating glucose metabolism at long-term, which could progressively lead to type 2 diabetes and other metabolic lifelong diseases." (PMID 33273510, 2020). "In patients with type 2 diabetes, the elevated serum triglyceride levels negatively correlate with circulating LPL levels, and positively with circulating APOC1, APOC3, ANGPTL3, ANGPTL4 and ANGPTL8 levels." (PMID 37448184, 2023). "Anti-ANGPTL3/IL22 fusion protein was expressed, purified and then examined for its protective efficacy and the possible mechanism in the db/db murine model of type 2 diabetes." (PMID 36544775, 2022). "Mean baseline ANGPTL3/8 and ANGPTL4/8 levels in these type 2 diabetes patients were 19 and 45 ng/ml, respectively." (PMID 32487544, 2020).
Hypercholesterolemia (19 papers, 2021 to 2025). An increased concentration of cholesterol in the blood. "The product of ANGPTL3 is the target of evinacumab, a human monoclonal antibody designed to treat hypercholesterolaemia." (PMID 38454133, 2024).